EYS (EGF-like photoreceptor maintenance factor)
Description:
Required to maintain the integrity of photoreceptor cells. Specifically required for normal morphology of the photoreceptor ciliary pocket, and might thus facilitate protein trafficking between the photoreceptor inner and outer segments via the transition zone (By similarity).
Synonyms: C6orf178; C6orf179; C6orf180; EGFL10; EGFL11; SPAM; dJ1018A4.2; bA166P24.2; bA307F22.3; dJ303F19.1; bA74E24.1; RP25; dJ22I17.2
Tractability: Antibody: UniProt places it where antibodies can reach, with high confidence; UniProt predicts a signal peptide or a membrane-spanning region; its Gene Ontology location is reachable by antibodies, with medium confidence.
Safety:
Unwanted effects reported when the protein is acted on. In parentheses: how it was acted on, where the effect was seen, and who reports it.
rhabdomyolysis (source: ClinPGx)
Gene: Protein-coding gene on chromosome 6 (63,719,980 to 65,707,226, reverse strand). Ensembl gene ENSG00000188107.
Subcellular location: Cell projection, cilium, photoreceptor outer segment; Cell projection, cilium; Cytoplasm, cytoskeleton, cilium axoneme; Cytoplasm, cytoskeleton, microtubule organizing center, centrosome; Secreted, extracellular space, extracellular matrix, interphotoreceptor matrix
Subcellular location (Human Protein Atlas): Cytosol; Flagellar centriole; Plasma membrane; Predicted to be secreted
Gene Ontology:
Molecular function: extracellular matrix structural constituent; calcium ion binding
Biological process: detection of light stimulus involved in visual perception; skeletal muscle tissue regeneration; developmental growth; nervous system process
Cellular component: centriole; extracellular exosome; non-collagenous component of interstitial matrix; axoneme; centrosome; cilium; cytoskeleton; interphotoreceptor matrix; photoreceptor outer segment
Genetic constraint (gnomAD): Loss-of-function variants: 176 observed, 207.69 expected, observed/expected ratio (o/e) 0.85, 90% interval 0.75 to 0.96. The upper end of that interval is the gene's LOEUF score, 0.96, which puts it in group 4 of 6, group 1 being the genes least tolerant of losing a copy. Missense variants: 3,265 observed, 3,195.1 expected, observed/expected ratio (o/e) 1.02, 90% interval 0.99 to 1.05. Synonymous variants: 1,141 observed, 1,129.1 expected, observed/expected ratio (o/e) 1.01, 90% interval 0.96 to 1.06.
Gene-disease validity (ClinGen):
ClinGen rates the evidence that EYS causes each of these diseases.
EYS-related retinopathy (autosomal recessive): Definitive. An inherited retinopathy caused by bi-allelic variants in the EYS gene.
Homologues: Orthologues: chimpanzee EYS (99% identical), macaque EYS (94% identical), Drosophila melanogaster frac (5% identical). Paralogues in human: FBLN2 (7% identical), FBLN1 (6% identical), VWDE (5% identical), EFEMP2 (4% identical), FBLN5 (4% identical), EFEMP1 (4% identical).
Diseases named in the same sentence as EYS in open-access papers:
EYS is named in the same sentence as 58 diseases in open-access papers, as found by Europe PMC text mining. Sharing a sentence is not in itself a finding about the gene and the disease. The quoted sentences say what the papers report.
retinitis pigmentosa (46 papers, 2009 to 2025). Retinitis pigmentosa (RP) is an inherited retinal dystrophy leading to progressive loss of the photoreceptors and retinal pigment epithelium and resulting in blindness usually after several decades. "This study compares clinical characteristics of retinitis pigmentosa (RP) associated with mutations in the EYS and USH2A genes in a Southeast Asian cohort." (PMID 39932467, 2025). "For example, a stop-gain variant (NM_001292009:c.C8608T:p.R2870X) in EYS, a common gene for retinitis pigmentosa in autosomal recessive mode, was detected in one homozygous macaque and in 20 heterozygous macaques." (PMID 38969634, 2024). "Pathogenic variants in EYS have been associated with a more severe clinical course compared to mutations in other retinitis pigmentosa (RP)-related genes." (PMID 39588395, 2024). "Among those, 74% (20/27) of variants were found in genes causally linked to Retinitis Pigmentosa (RP), with the gene EYS being the most frequently affected by SVs." (PMID 38245557, 2024). "This research has provided new information concerning patients affected by Retinitis Pigmentosa associated with EYS gene mutations." (PMID 36899994, 2023). "These six SP variants were in the CRB1 (early-onset retinal dystrophy), NDP (familial exudative vitreoretinopathy) (FEVR), FZD4 (FEVR), EYS (retinitis pigmentosa), and RS1 (X-linked juvenile retinoschisis) genes." (PMID 36362148, 2022). "Mutations in the extracellular matrix protein eyes shut homolog (EYS) are a common cause of retinitis pigmentosa, a blinding disease characterized by photoreceptor degeneration." (PMID 36499139, 2022). "They demonstrate that one of these variants (G843E) causes retinal dysfunction in zebrafish, suggesting a causal role for EYS in retinitis pigmentosa." (PMID 33514863, 2021). "And zebrafish (Danio rerio) is the only model in which loss-of-function mutations in the homologous eys have been shown to recapitulate photoreceptor degeneration observed in retinitis pigmentosa patients with EYS mutations." (PMID 33514863, 2021). "Mutations in another gene in our model, eyes shut homolog (EYS), have mainly been connected to ophthalmologic diseases, such as retinitis pigmentosa." (PMID 34621291, 2021). "The Eyes shut homolog (EYS) gene was identified as the causing gene for retinitis pigmentosa 25 (RP25) (OMIM 612424, NM_001142800) in 2008." (PMID 34001227, 2021). "This strongly suggests that the G843E allele contributes to retinitis pigmentosa in trans with another EYS mutation, as in ARRP." (PMID 33514863, 2021). "The purpose of our study was to illustrate a data-driven deep learning approach to predict the causative genes of IRD in macular dystrophy caused by ABCA4 and RP1L1 in comparison with retinitis pigmentosa caused by EYS gene aberration and normal subjects." (PMID 31093368, 2019). "Mutations in the EYS (eyes shut homolog) gene are a common cause of autosomal recessive (ar) retinitis pigmentosa (RP)." (PMID 28704921, 2017). "Mutations in the EYS (eyes shut homolog) gene, originally designated as the RP25 locus on chromosome 6q12, are a major cause of autosomal recessive (ar) retinitis pigmentosa (RP)." (PMID 28704921, 2017). "Mutations in the extracellular matrix protein eyes shut homolog (EYS) cause photoreceptor degeneration in patients with retinitis pigmentosa 25 (RP25)." (PMID 27737822, 2016). "The EYS gene has recently been identified as the disease-causing gene for retinitis pigmentosa, and encodes an orthologue of Drosophila spacemaker." (PMID 20696082, 2010). "The EYS gene is a recently identified disease-causing gene for retinitis pigmentosa, and encodes the orthologue of Drosophila spacemaker." (PMID 20696082, 2010). "However, further screening of this patient by NGS-retina panel sequencing revealed a homozygous pathogenic EYS variant (NM_001142800.2) c.8648_8655del p.(Thr2883Lysfs*4) associated with retinitis pigmentosa 25 (OMIM #602772)." (PMID 39087934, 2024).
retinitis pigmentosa (continued). "Taken together, the G843E mutation may cause retinitis pigmentosa when both alleles of EYS are affected, either in a compound heterozygous or a homozygous state, as observed in an ARRP allele." (PMID 33514863, 2021). "The EYS gene was first reported to cause retinitis pigmentosa and associated phenotypes in 2008." (PMID 34178978, 2021). "Although autosomal recessive single-nucleotide mutations in EYS have been reported in patients with retinitis pigmentosa, the role of heterozygous microdeletions involving this gene is unknown." (PMID 22102821, 2011). "Notably, mutations in previously reported AAU-related gene EYS also lead to retinitis pigmentosa." (PMID 32492107, 2020). "Pathogenic variants in the EYS (eyes shut homolog) and USH2A (Usher syndrome type 2A) genes are responsible for a substantial proportion of retinitis pigmentosa (RP) worldwide and are the most prevalent genetic causes of RP in East Asia." (PMID 39932467, 2025). "In our data, CRB1 and EYS were related to the development of the autosomal recessive disorder retinitis pigmentosa (RP)." (PMID 34977041, 2021). "Mutations in eyes shut homolog (EYS), a gene predominantly expressed in the photoreceptor cells of the retina, are among the most frequent causes of autosomal recessive (ar) retinitis pigmentosa (RP), a progressive retinal disorder." (PMID 30052645, 2018). "For retinitis pigmentosa, variants of USH2A and EYS were the most common causative gene mutations." (PMID 33691693, 2021).
autosomal recessive retinitis pigmentosa (25 papers, 2010 to 2025). Autosomal recessive retinitis pigmentosa (RP) is an autosomally recessive inherited retinal dystrophy leading to progressive loss of the photoreceptors and retinal pigment epithelium and resulting in blindness usually after several decades. "Mutations in human EYS (RP25) are a major cause of autosomal recessive retinitis pigmentosa, characterized by progressive photoreceptor loss." (PMID 40520108, 2025). "Eyes shut homolog (EYS) is a major causative gene of autosomal recessive retinitis pigmentosa (RP), particularly prevalent in Asian countries, including Japan." (PMID 40989003, 2025). "The EYS gene is one of the principal genes associated with autosomal recessive retinitis pigmentosa (arRP)." (PMID 39588395, 2024). "Pathogenic variants in the eyes shut homolog (EYS) gene are estimated to affect at least 5% of patients with autosomal recessive retinitis pigmentosa (arRP)." (PMID 36899994, 2023). "Eyes shut homolog (EYS) gene mutations are estimated to affect at least 5% of patients with autosomal recessive retinitis pigmentosa." (PMID 36899994, 2023). "Mutations in the EYS gene are a common cause of autosomal recessive retinitis pigmentosa (arRP) in Chinese and Japanese sub-populations, yet the role of EYS PG in humans remains to be fully determined." (PMID 36674659, 2023). "EYS is expressed in the photoreceptor layer of the retina, and a mutation in EYS plays a role in autosomal recessive retinitis pigmentosa." (PMID 28484645, 2017). "Mutations in the EYS gene are the commonest cause of non-syndromic autosomal recessive retinitis pigmentosa (arRP; OMIM #602772)." (PMID 27846257, 2016). "Mutations in the EYS gene are a common cause of autosomal recessive retinitis pigmentosa (arRP), yet the role of the EYS protein in humans is presently unclear." (PMID 27846257, 2016). "Human EYS, which is mutated in patients with autosomal recessive retinitis pigmentosa, also harbors multiple Rumi target sites." (PMID 25412384, 2014). "The EYS gene has been associated with autosomal recessive retinitis pigmentosa (arRP)." (PMID 39588395, 2024). "Biallelic variants in EYS are the major cause of autosomal recessive retinitis pigmentosa (arRP) in certain populations, a clinically and genetically heterogeneous disease that may lead to legal blindness." (PMID 38704576, 2024). "EYS gene - is a Protein Coding gene – which is mutated in autosomal recessive retinitis pigmentosa." (PMID 35413811, 2022). "Mutations in the EYS gene are one of the major causes of autosomal recessive retinitis pigmentosa." (PMID 34001227, 2021). "Interestingly, mutations in the human orthologues Prominin 1 (PROM1) and EYS are associated with autosomal-recessive retinitis pigmentosa and macular degeneration." (PMID 24705015, 2014). "I identified the entire exon sequence of the eyes shut homolog (EYS) gene in patients with autosomal recessive retinitis pigmentosa (RP)." (PMID 39271608, 2024). "Eyes shut homolog (EYS; OMIM: 612424), spanning approximately 2 Mb of chr6q12 and consisting of 44 exons, was first reported in 2008 as a disease-causing gene for autosomal recessive retinitis pigmentosa (RP)." (PMID 34689181, 2022). "The eyes shut homolog (EYS; OMIM: 612424) is a major disease-causing gene for autosomal recessive retinitis pigmentosa, and is mainly found in Chinese and Japanese populations, where it has a prevalence ratio of about 11% and 32.8%, respectively." (PMID 34178978, 2021). "The EYS gene was reported to be the most common gene responsible for autosomal recessive retinitis pigmentosa (arRP)." (PMID 30359287, 2018). "Of note, mutations in human EYS and PROM1 cause several forms of retinal degeneration including autosomal recessive retinitis pigmentosa, rod-cone dystrophies and cone-rod dystrophy." (PMID 25412384, 2014).
autosomal recessive retinitis pigmentosa (continued). "Another significant example lies in mutations in the EYS gene, one of the primary causes of autosomal recessive retinitis pigmentosa; however, there is no suitable model to study this disease, as EYS is not conserved in murine models." (PMID 40244125, 2025). "Known genetic defects were excluded by performing autosomal recessive retinitis pigmentosa (arRP) genotyping microarray analysis and by Sanger sequencing of the coding exons and flanking intronic regions of eyes shut homolog–drosophila (EYS) and chromosome 2 open reading frame 71 (C2orf71)." (PMID 21738389, 2011).
Retinal dystrophy (14 papers, 2013 to 2025). Retinal dystrophy is an abnormality of the retina associated with a hereditary process. "For EYS-associated retinal dystrophy, a high-capacity helper-dependent adenoviral vector (HDAdV) was employed to deliver the full-length EYS gene, successfully rescuing protein mislocalization in organoids." (PMID 39422807, 2025). "Our prior study reported that the prevalence of EYS mutations in patients with inherited retinal dystrophies (IRDs) was 7% in the Chinese population, and EYS mutations were ranked as the third most common genetic mutation in patients with IRD." (PMID 34689181, 2022). "EYS is missing or interrupted in the genome of several mammalian lineages, including the most common animal models: mouse, rat, and guinea pig, and this has made it difficult to investigate EYS-associated retinal dystrophies (EYS-RDs)." (PMID 38646933, 2024). "This retrospective study of 420 well-documented IRD cases with mutations in the EYS gene included 39 patients from a genotype-phenotype study of inherited retinal dystrophy (IRD) conducted at the Beijing Institute of Ophthalmology and 381 cases retrieved from global reports." (PMID 34178978, 2021). "Consistent with this, a previous study on RP1-associated retinal dystrophies indicated oligogenicity in 28 patients with the RP1 variant (p.Arg1933Ter) in one allele, in whom two identified EYS variants were significantly enriched." (PMID 34073704, 2021). "The clinical manifestation of a dysfunctional POMGTn1, leading to retinal dystrophy, might be mediated by a defective interaction between EYS and the extracellular matrix." (PMID 34001227, 2021). "After identifying the EYS gene, patients presenting retinal dystrophy without a genetic diagnostic were tested for mutations in this gene, revealing it as the major gene for non-syndromic arRP." (PMID 34001227, 2021). "In addition to CEP290, several other of the most frequently mutated inherited retinal dystrophy genes, e.g., ABCA4, EYS, and USH2A have a cDNA size way exceeding this limit and hence are not amenable for AAV-based gene therapy." (PMID 26325627, 2015). "However, this heterozygous EYS variant was not considered causative for her retinopathy because EYS variants have been reported to lead to EYS-associated retinal dystrophy only in the biallelic condition." (PMID 32079136, 2020). "In addition, several genes in which mutations are causative for retinal dystrophy in humans do not have an orthologue in rodent species, like for instance EYS." (PMID 24223178, 2013). "Studies have reported that USH2A, EYS and CRB1 are the top three genes responsible for inherited retinal dystrophy." (PMID 34977041, 2021). "A previous study showed that USH2A, EYS, and CRB1 were the top three genes contributing to inherited retinal dystrophy in Chinese patients." (PMID 31269016, 2019).
retinal degeneration (11 papers, 2014 to 2025). Degeneration of the retina. "This potentially explains the atypical patterns of retinal degeneration in a subset of patients with EYS RP, wherein loss of EYS function results in retinal phototoxicity and degeneration." (PMID 39932467, 2025). "The data reported in this study qualifies the SRI in the detection of iRORA as an important parameter concerning the rate of progression of retinal degeneration caused by biallelic mutations in the EYS gene." (PMID 36899994, 2023). "The deleted region encompasses the exons 1 to 12 and 5’-untranslated region of the EYS gene implicated in recessive retinal degeneration (Fig 3A2)." (PMID 34662339, 2021). "Therefore, the exact molecular function of EYS and how mutant EYS causes retinal degeneration are yet to be elucidated." (PMID 38646933, 2024). "In fact, it was reported that patients with pathogenic variants in some specific genes, including EYS and RHO, exhibit such patterns of retinal degeneration." (PMID 38646933, 2024). "Some authors suggested that a different phenotype and progression in EYS-related retinal degeneration could be related to the specific EYS genotype." (PMID 36899994, 2023). "Some other retina degeneration animal models such as CC2D2A, RP2, and EYS are characterized by opsin mislocalization and further photoreceptor cell loss, and these genes are associated with cilia transport." (PMID 37351277, 2023).
cone-rod dystrophy (10 papers, 2010 to 2024). Inherited retinal dystrophies that belong to the group of pigmentary retinopathies. "Although human EYS variants usually cause RP, in some patients cone cell degeneration precedes that of rod cells, exhibiting cone rod dystrophy or macular dystrophy." (PMID 38646933, 2024). "Patients with EYS mutations present with a typical RP phenotype, but there are also reports of cone-rod dystrophy caused by EYS mutations." (PMID 36513702, 2022). "Mutations in the EYS gene cause a variety of phenotypes such as RP and cone-rod dystrophy characterised by inter- and intrafamilial phenotypic diversities." (PMID 33833316, 2021). "EYS mutations typically cause RP in human patients, although EYS mutations have also been associated with a cone-rod dystrophy." (PMID 33435268, 2021). "Mutations in EYS have been commonly found in individuals suffering from arRP; nonetheless, one case of cone-rod dystrophy caused by a compound heterozygous mutation in EYS has been reported." (PMID 27846257, 2016). "In light of the report of a case of cone-rod dystrophy caused by mutations in EYS, this finding leads to a conclusion that EYS is also vital for the proper functioning of cones." (PMID 27846257, 2016). "Of note, there has been a report of a Japanese individual diagnosed with cone-rod dystrophy caused by a compound heterozygous mutation in EYS." (PMID 27846257, 2016). "By analysis of the physiological and pathological progression from 10 dpf to 16 mpf, we concluded that loss of EYS in zebrafish mainly leads to cone and rod dystrophy, and our detailed description of the pathological processes in EYS−/− zebrafish would be useful references for clinical diagnosis." (PMID 28378834, 2017). "The other IRD group included Stargardt's disease carrying ABCA4 variants, as well as individuals with Cone-Rod Dystrophy (CORD) or RP presenting with various genetic variants such as RDH12, RPGR, LCA5,CEP290, RP2, USH2A, and EYS." (PMID 38466290, 2024).